MIR4271 (microRNA 4271)
Synonyms: hsa-mir-4271
Gene: MicroRNA gene on chromosome 3 (49,274,120 to 49,274,186, forward strand). Ensembl gene ENSG00000264633.
Homologues: Orthologues: chimpanzee MIR4271 (100% identical).